SEC62 (SEC62 preprotein translocation factor)
Diseases named in the same sentence as SEC62 in open-access papers (continued):
Sharing a sentence is not in itself a finding about the gene and the disease.
lymph node metastasis (5 papers, 2013 to 2023). "Together with our previous findings that SEC62 is overexpressed and correlates with lymph node metastasis (N + vs." (PMID 24304694, 2013). "We found that SEC62 positivity of tumor cells in pre-therapeutic samples was a significant and independent prognostic factor indicating a shorter overall survival and significantly correlated with advanced lymph node metastases, p16 positivity, and chronic tobacco exposure." (PMID 38201525, 2023).
non-small cell lung carcinoma (5 papers, 2017 to 2022). A group of at least three distinct histological types of lung cancer, including non-small cell squamous cell carcinoma, adenocarcinoma, and large cell carcinoma. "In non-small cell lung cancer, high Sec62 levels correlated with the occurrence of lymph node metastases and poor tumor differentiation." (PMID 33925740, 2021).
viral infection (4 papers, 2021 to 2023). "Interestingly, in both Sec62 and Chmp4-depleted cells, defective virus production upon Ube2g2-deficiency was rescued to wild-type levels, in support of the hypothesis that Ube2g2 inhibits this pathway during virus infection." (PMID 37164963, 2023). "Upon activation of SEC62 via viral infection, activated SEC62 drives IRE1α phosphorylation, which subsequently induces the IRE1-JNK pathway and delivers autophagosomes to lysosomes, thus mitigating virus-induced ER stress and impeding viral replication." (PMID 37266445, 2023). "Sec62 knockdown led to elevated viral production, while overexpression of Sec62 inhibited viral replication by enhancing viral infection-triggered ER-phagy." (PMID 34912806, 2021). "Our study adds to mounting evidence that SEC62 is important for viral infections, but further investigation is warranted to interrogate if the mechanism behind our SARS-CoV-2 finding is due to modulation of autophagy, ER stress, and/or transmembrane protein translocation for cell-surface expression." (PMID 37803001, 2023).
melanoma (3 papers, 2021 to 2023). A malignant, usually aggressive tumor composed of atypical, neoplastic melanocytes. "As Clark level is established as a relevant prognostic factor in the initial assessment of melanomas, SEC62 expression was compared in primary melanomas with Clark levels ranging from two to five." (PMID 33915997, 2021). "Significantly higher Sec62 levels were found in melanomas with lymph node and distant metastases compared with those without." (PMID 33915997, 2021). "The markedly elevated Sec62 levels in malignant compared to benign melanocytic tumors indicates an oncogenic function of SEC62 in melanoma carcinogenesis." (PMID 33915997, 2021). "In melanoma patients, high Sec62 levels correlated with shorter overall and progression-free survival." (PMID 33915997, 2021). "First, overall survival (OS) and progression-free survival (PFS) were compared for melanoma patients with high (IRS 8–12) vs. low (IRS 0–7) SEC62 expression and for patients with different T stages." (PMID 33915997, 2021). "This study is the first in the literature to investigate the role of the 3q oncogene, SEC62, in human melanocytic tumors and provides the first evidence for the role of Sec62 as a prognostic biomarker in melanoma." (PMID 33915997, 2021). "To explain this observation, we would have to compare SEC62 expression in SN versus spitzoid melanomas and analyze if there is again an increase in SEC62 expression from SN to spitzoid melanoma." (PMID 33915997, 2021). "The functional role of Sec62 in malignant melanoma, as well as its role as a potential therapeutic target, must be evaluated in further studies." (PMID 33915997, 2021). "As, to date, we rely on descriptive data based on immunohistochemical stainings, valid information on the potential role of SEC62 in the tumor cell biology of melanoma cells remains elusive." (PMID 33915997, 2021). "Taken together, these data suggest a relevant role of SEC62 as a metastasis-stimulating oncogene in melanoma development, which represents a promising therapeutic target." (PMID 33915997, 2021). "For the group of malignant melanocytic lesions, we included primary melanomas (MM) as well as distant metastases of melanomas (MET) in order to see if there are differences in SEC62 expression between primary tumor tissue and tissue with a presumably higher metastatic potential." (PMID 33915997, 2021). "Since 3q amplifications are not a frequent finding in melanoma cells, the observed high Sec62 protein levels presumably are a result of specific SEC62 gains and/or overexpression." (PMID 33915997, 2021). "Accordingly, we found a significant correlation of high Sec62 levels in primary melanoma with the development of lymph node and distant metastases." (PMID 33915997, 2021). "Sec62 showed significantly higher expression in primary melanomas with ulceration in comparison with those without (p = 0.002)." (PMID 33915997, 2021).
ovarian carcinoma (3 papers, 2009 to 2022). A malignant neoplasm originating from the surface ovarian epithelium. "Our analyses of the TCGA data, which showed alterations of this gene (mostly amplifications) in 39% of all cases, underlines the potential role of SEC62 as a key tumor-driver gene in ovarian cancer." (PMID 36685175, 2022). "This study revealed an increased incidence of SEC62 alterations and a correlation between high SEC62 expression and worse OS in patients with ovarian cancer." (PMID 36685175, 2022). "With the identification of Sec62 as a potential prognostic marker for OS in patients with ovarian cancer, questions remain for further study." (PMID 36685175, 2022). "In this study, we found that SEC62 is overexpressed in ovarian cancer cells, SEC62 expression can serve as a prognostic marker for patients with ovarian cancer or borderline tumor of the ovary and SEC62 is a potential tumor-driver gene accounting for 3q amplification in ovarian cancer." (PMID 36685175, 2022). "For the prognostic role of SEC62, we could identify an IRS of >9 being associated with a shortened overall survival for patients with ovarian cancer, as well as for patients with borderline tumors of the ovary." (PMID 36685175, 2022). "We observed cytoplasmic Sec62 positivity in all ovarian cancer and borderline ovarian tumor cells, but not in physiological ovarian tissue cells." (PMID 36685175, 2022).
cervical dysplasia (2 papers, 2006 to 2016). "Expression levels of Sec62 and vimentin were analyzed in liquid based cytology specimens from 107 women with varying grades of cervical dysplasia ranging from normal cases to cancer by immunofluorescence cytology." (PMID 27553742, 2016).
COVID-19 (1 paper, 2022). A disease caused by infection with severe acute respiratory syndrome coronavirus 2. "Conversely, for most of the other genes (7 out of 9) in this superset, downregulation correlated increased HRs of COVID-19 mortality, including two genes (SEC62 and SGTB) that target ER and participate in degradation of misfolded proteins." (PMID 35547187, 2022).
hypopharyngeal squamous cell carcinoma (1 paper, 2022). "For further investigation of the role of SEC62 in HNSCC, especially in the proliferation and migration behaviour of HNSCC cancer cells, an immortalized cell line of a hypopharyngeal squamous cell carcinoma (FaDu) was used." (PMID 36045752, 2022).
intraepithelial neoplasia (1 paper, 2016). A precancerous neoplastic process that affects the squamous, glandular, or transitional cell epithelium without evidence of invasion. "The IFC analyses indicated that SEC62 overexpression marks the transition from intraepithelial neoplasia to an invasive phenotype." (PMID 27553742, 2016).
mental disorder (1 paper, 2020). A disease that has its basis in the disruption of mental process. "Three (COX5B, SEC62, and NDUFA2) were validated with another technique and were also differentially regulated in postmortem brain of subjects with mental disorders." (PMID 32184383, 2020). "Although no study investigated this gene in mental disorders, SEC62 was among the differentially expressed genes in ASD brain samples, showing decreased transcript levels." (PMID 32184383, 2020).
parasitemia (1 paper, 2024). "Three modules led by the hub genes RIOK3, CSDE1, and SEC62 negatively associated with protection and positively associated with both prevaccination anti–CSP IgG and parasitemia at first vaccination." (PMID 38687615, 2024).
skin cancer (1 paper, 2021). "Only one study addressed the role of SEC62 in skin cancer so far, which focused on 41 cases of atypical fibroxanthomas (AFX)." (PMID 33915997, 2021).
Zellweger syndrome (1 paper, 2025). "This problem originally also occurred after transient depletion of PEX3, Sec62, and Sec63 and was the reason for the use of CRISPR/Cas9-mediated Sec62- as well as Sec63-knock-out cells or fibroblasts from PEX3-deficient Zellweger Syndrome patients." (PMID 41009394, 2025).
cancer (27 papers, 2013 to 2024). A tumor composed of atypical neoplastic, often pleomorphic cells that invade other tissues. "SEC62 represents a metastasis stimulating oncogene that is frequently overexpressed in various cancer entities and is associated with poor outcome." (PMID 38201525, 2023). "High SEC62 expression levels were observed in various cancer entities and were associated with a poor outcome and increased metastatic burden." (PMID 36045752, 2022). "Recent studies substantiated that the dysfunction of Sec62 frequently occurs in various cancers, which is tightly associated with tumour malignant behaviours." (PMID 36200182, 2022). "SEC62 overexpression is associated with reduced survival and progression-free survival in cancer patients." (PMID 36497032, 2022). "Amplification and overexpression of the SEC62 oncogene was reported in a variety of human cancers and was associated with poor prognosis as well as lymph node and distant metastases." (PMID 33915997, 2021). "Amplification and/or over-expression of the SEC62 gene (also termed TLOC1) were linked to various cancers and appear to be associated with poor prognosis." (PMID 29163222, 2017). "Overproduction of components of the protein translocation machinery is associated with cancers of prostate, lung, head, and neck (Sec62) and with glioblastoma (Sec61γ)." (PMID 29163222, 2017). "The generation of SEC62-knockout clones was an important step to build a basement for further basic research in order to elucidate the molecular backgrounds underlying the clinical effects of a SEC62 overexpression in human cancer." (PMID 36045752, 2022). "Additionally, higher SEC62 levels are linked to larger tumor size, tumor ulceration, and distant metastases in the various cancer types." (PMID 36497032, 2022). "FAM134B and Sec62 have been found to be associated with cancer." (PMID 35452617, 2022). "For the SEC62 gene encoded at chromosomal region 3q26.2, increasing evidence suggests a relevant role in human carcinogenesis and tumor cell biology, especially in cancer metastasis and invasiveness." (PMID 33915997, 2021). "Therefore, in the present study, we tested whether lower Sec62 levels in cancer tissue are associated with longer patient survival, which would indicate whether Sec62 can serve as a prognostic marker." (PMID 24304694, 2013). "Over the past several years, increasing evidence has suggested a relevant role of SEC62 in human cancer." (PMID 38201525, 2023). "In vitro studies conducted with tissue samples and cancer cell lines have shown that SEC62 is overexpressed in tumors relative to tumor-free tissue at the protein and mRNA levels in lung, prostate, head and neck, and cervical cancers." (PMID 37298528, 2023). "Recently, a pan-cancer analysis using DNA sequencing data from over 40,000 patients showed that SEC62 gene amplification represents a highly significant indicator of poor overall survival." (PMID 38201525, 2023). "As potentially underlying molecular mechanisms, in vitro studies showed that SEC62 drives cancer metastasis by activating the MAPK/ATF2/UCA1 axis, mediating UPR-induced autophagy activation, and limiting calcium efflux across the ER membrane." (PMID 38201525, 2023). "Other potential strategies to inhibit SEC62 function in human cancer cells include the use of autophagy inhibitors such as hydroxychloroquine." (PMID 38201525, 2023). "Strikingly, plasmid-driven overexpression of SEC62 in non-SEC62 overexpressing cells introduces the same three hallmarks of cancer into the transfected cells." (PMID 36262254, 2022). "In human colorectal cancer, upregulated SEC62 enhances cancer stemness and progression through triggering Wnt/β-catenin signaling and is associated with the poor prognosis in patients." (PMID 35327508, 2022). "Amplification of SEC62 is assumed to induce ER stress tolerance in tumor cells, thus likely inducing high metastatic potential in these cancers." (PMID 35452617, 2022).
cancer (continued). "These cell lines will be subject of further investigations to shed light on the function of SEC62 in various processes in HNSCC cancer cell biology." (PMID 36045752, 2022). "Studies have found that in non-small cell lung cancer (NSCLC) and thyroid cancer, the high expression of SEC62 can make cancer cells more resistant to UPR and other ER-stress, and thus promote the invasion and migration of cancer cells." (PMID 34571977, 2021). "An influence of SEC62 expression level on stress tolerance of human cancer cells was suggested by several studies reporting a higher sensitivity to ER stress induced by CaM inhibitors when SEC62 is expressed at low levels." (PMID 33925740, 2021). "Highest evidence for a causative role of a protein translocation component in the development and tumor cell biology of human cancer exists for the ER transmembrane protein Sec62." (PMID 33925740, 2021). "Since chemoresistance is a key feature of cancer stemness, we wanted to know if Sec62 modulates the stemness of CRC cells." (PMID 33858476, 2021). "We further demonstrated that Sec62 promotes cancer stemness and CRC progression through enhancing Wnt/β-catenin signaling." (PMID 33858476, 2021). "Since human Sec62 has dual functions as a translocation component and a receptor for ER-specific autophagy, its role in cancer requires further investigation." (PMID 34884562, 2021). "In this study, SEC62 expression was analyzed in benign, borderline, and malignant melanocytic lesions of 209 patients." (PMID 33915997, 2021). "Overexpression of 3q26 encoded genes SEC62 and SOX2 was detected in various cancers, including HNSCCs, indicating their potential function as oncogenes." (PMID 28002801, 2017). "As in the first part of our study FISH- and IFC-analyses indicated a potential oncogenic function of SEC62, we sought to identify a functional correlate in cancer cell biology using HeLa cells an in vitro model." (PMID 27553742, 2016). "However, for SEC62 encoding for an endoplasmic reticulum transmembrane protein involved in intracellular protein transport, we previously reported that overexpression of SEC62 increases the migration ability of different human cancer cells as a basic mechanism of metastasis." (PMID 27553742, 2016). "We have previously reported strong inhibition of cell migration in different human cancer cells after Sec62 depletion by transfection with SEC62 siRNA." (PMID 24304694, 2013). "In the current study, we showed that treatment of different human cancer cells with calmodulin antagonists induced a Sec62-depletion phenotype, including cell migration inhibition and higher sensitivity to Ca2+-driven ER stress." (PMID 24304694, 2013). "These combined observations imply that SEC62-mediated ER-phagy may aid cancer cells in better coping with endoplasmic reticulum stress and aid in their survival and migration." (PMID 38262996, 2024). "High levels of SEC62 expression have been associated with increased resistance to UPR and other endoplasmic reticulum stress in non-small cell lung cancer and thyroid cancer cells, which facilitates cancer cell invasion and migration." (PMID 38262996, 2024). "Furthermore, cancer cells benefit from high SEC62 expression levels through improved recovery from ER stress conditions which are not only induced by a high protein turnover due to elevated proliferation rate, but also by radiotherapy." (PMID 38201525, 2023). "As it was shown that high SEC62 expression levels allow human cancer cells to better compensate ER stress conditions, HNSCCs might tolerate higher radiation doses once they overexpress SEC62." (PMID 38201525, 2023). "A previous study of our group could show that the migration stimulating effect as well as the better tolerance of ER-stress in SEC62 overexpressing cancer cells can be inhibited by SEC62 silencing, which was shown to be a Ca2+ dependent process." (PMID 36045752, 2022).